AR (androgen receptor)
Diseases named in the same sentence as AR in open-access papers (continued):
Sharing a sentence is not in itself a finding about the gene and the disease.
Pancytopenia (1 paper, 2025). An abnormal reduction in numbers of all blood cell types (red blood cells, white blood cells, and platelets). "After androgen deprivation therapy (goserelin) along with an androgen receptor antagonist (darolutamide), the patient’s serum total PSA level declined drastically to 0.01ng/ml, accompanied by an improvement in pancytopenia." (PMID 41018093, 2025).
papillary serous adenocarcinoma (1 paper, 2006). "Immunoreactivity with AR was noted in 2 of these tumors, a papillary serous adenocarcinoma and the other mixed endometriod – papillary serous adenocarcinoma." (PMID 17020615, 2006).
paraganglioma (1 paper, 2021). A benign or malignant neoplasm arising from paraganglia located along the sympathetic or parasympathetic nerves. "The tumor was negative for thyroid, parathyroid and paraganglioma markers, but positive for pan-cytokeratins, CK7, CD10, CD117, androgen receptor and HNF-beta." (PMID 32519264, 2021).
Penile hypospadias (1 paper, 2012). Location of the urethral opening on the inferior aspect of the penis. "It has also been reported that other polymorphisms, such as longer GGN repeat lengths in the AR, increase the risk for penile hypospadias." (PMID 23167717, 2012).
peritonitis (1 paper, 2014). Inflammation of the peritoneum (tissue that lines the abdominal wall and covers most of the organs in the abdomen). "Analysis of IL-6 AR as well as sensitivity analyses in a peritonitis-free cohort yielded comparable results." (PMID 24410736, 2014). "Similar results were obtained when analyses were repeated in the peritonitis-free cohort as well as when IL-6 AR was analysed as the outcome." (PMID 24410736, 2014).
primary hypogonadism (1 paper, 2023). "One exception would be when the LH level is raised and there is a concern about subclinical/compensated primary hypogonadism or androgen receptor cytosine, adenine, guanine (CAG) repeat polymorphism." (PMID 38132234, 2023).
psoriasis (1 paper, 2013). An autoimmune condition characterized by red, well-delineated plaques with silvery scales that are usually on the extensor surfaces and scalp. "Many DEG-coded proteins (CCNA2, FYN, PIK3R1, CTGF, F3) and transcription factors (AR, TFDP1, MEF2A, MECOM) were identified as central nodes, suggesting their potential role in psoriasis pathogenesis." (PMID 24303025, 2013).
ptosis (1 paper, 2020). The drooping of the upper eyelid. "We noticed that AR-OI patients carrying WNT1 mutations were prone to developing ptosis, with 46.67% penetrance." (PMID 33093841, 2020).
renal pelvis cancers (1 paper, 2025). A carcinoma arising in the renal pelvis. "In an analysis of 99 cases of UTUC, androgen receptor (AR) was present in approximately 20% of tumours, and AR expression was higher in ureteral cancers than in renal pelvis cancers and tended to be more present in men than in women." (PMID 41514635, 2025).
Reovirus infection (1 paper, 2022). "Reovirus infection was observed in both AR-positive and AR-negative PDX models." (PMID 34135475, 2022).
reproductive system cancer (1 paper, 2022). "AR is a well-defined receptor for A in female reproductive system cancers, and AR has attracted great interest as a potential therapeutic target." (PMID 35886904, 2022). "Although efforts have been made to explore the effects and mechanisms of AR on female reproductive system cancer, further research needs to be conducted in preclinical trials." (PMID 35886904, 2022).
retinal cone dystrophy type 3B (1 paper, 2024). "The previous nonsense mutation is present in the population database (GnomAD exomes, number of homozygous alleles = 0) at an exceedingly low frequency (8:627,570 alleles, 0.00001275), the variant affecting the KCNV2 gene, which is associated with retinal cone dystrophy type 3B (610,356; AR)." (PMID 39200733, 2024).
retinal degeneration (1 paper, 2015). Degeneration of the retina. "Expression of a polyQ-expanded 130 amino acid N-terminal fragment of AR (trAR112Q) in the Drosophila eye results in a robust retinal degeneration and depigmentation phenotype." (PMID 26308581, 2015). "Co-expression of NLK-WT enhanced the retinal degeneration phenotype and, more strikingly, dramatically increased the mutant AR aggregation detected by immunoblot (lane 4 vs lane 6)." (PMID 26308581, 2015). "Interestingly, a separate study found that the retinal degeneration phenotypes in a full-length mutant AR Drosophila model were also dependent upon the AF-2 domain of AR." (PMID 26308581, 2015). "Importantly, we also found that expression of kinase-dead NLK-KN did not enhance the retinal degeneration phenotype or mutant AR aggregation (lane 4 vs lane 7), a finding consistent with our cell culture data." (PMID 26308581, 2015).
schwannoma (1 paper, 2013). A benign, usually encapsulated slow growing tumor composed of Schwann cells. "Androgen receptor downregulation: A hormonal cause or consequence of schwannomas?" (PMID 23354516, 2013). "Our results demonstrated that the mRNA levels of both transcripts were downregulated, suggesting that there may be a mechanism by which AR and CAV1 are related to the development and/or maintenance of schwannomas." (PMID 23354516, 2013). "We therefore selected genes that were well-established as deregulated in these tumors to verify our results and then focused on deregulated genes in other tumors, as well as in our series, that had been insufficiently studied or not studied at all in schwannomas, such as MET, AR or CAV1." (PMID 23354516, 2013).
scoliosis (1 paper, 2025). A congenital or acquired spinal deformity characterized by lateral curvature of the spine. "(2023) showed that 71% patients with AR mutations presented signs at birth, 19% had contractures including contractures of the neck, shoulder, elbow, wrists, thumb, hip, knee and ankles at birth, 23% had scoliosis, and 29% had spinal rigidity." (PMID 41091627, 2025).
Seizure (1 paper, 2025). A seizure is an intermittent abnormality of nervous system physiology characterized by a transient occurrence of signs and/or symptoms due to abnormal excessive or synchronous neuronal activity in the brain. "Seizures are a serious AE specifically associated with AR signaling inhibitors." (PMID 40068144, 2025).
severe combined immunodeficiency (1 paper, 2021). Severe combined immunodeficiency (SCID) comprises a group of rare monogenic primary immunodeficiency disorders characterized by a lack of functional peripheral T lymphocytes resulting in early-onset severe respiratory infections and failure to thrive. "Adenosine deaminase (ADA) deficiency is one of the most common forms of severe combined immunodeficiency (SCID) that arises through AR inherited mutations in the ADA gene, encoding an enzyme involved in the purine salvage pathway." (PMID 34867986, 2021).
Sjögren’s syndrome (1 paper, 2017). "Indeed, Sjögren’s syndrome patients demonstrate marked decreases in their serum DHEA and androgen levels and reduced androgen receptor activity, as revealed by the decreased expression of CRISP-3." (PMID 28877240, 2017).
spinal meningioma (1 paper, 2022). Spinal meningioma isa rare type of spinal cord cancer. "Spinal meningiomas expressed more androgen receptors (AR+) and estrogen receptors (ER+) than intracranial meningiomas." (PMID 36713513, 2022).
spindle cell lipoma (1 paper, 2025). A benign circumscribed tumor composed of spindled cells, adipocytes, and collagen bundles. "The term “spindle cell lipoma” was initially introduced by Enzinger and Harvey in 1975, with a noticeable male predominance, particularly in the sixth decade, possibly linked to androgen receptor reactivity." (PMID 40224240, 2025).
Stickler syndrome (1 paper, 2020). Stickler syndrome is an inherited vitreoretinopathy characterized by the association of ocular signs with more or less complete forms of Pierre-Robin sequence, bone disorders, and sensorineural deafness (10% of cases). "The fact that COL9A3 is also annotated as AR in Orphanet (ORPHA:250984, Stickler syndrome) is not taken into account in the current implementation of the omimPrioritiser option." (PMID 32340307, 2020).
stomach diseases (1 paper, 2016). "In Sanhe Decoction, M4 (Kaempferol), M16 (Sugeonyl acetate), M23 (Przewalskin A), M24 (Przewalskin B), M39 (Microstegiol), M43 (Miltirone II) and M48 (Salvilenone I) were identified to block AR, highlighting therapeutic effects of on the stomach diseases." (PMID 27597117, 2016).
sweat gland tumor (1 paper, 2025). "Anti‐androgen therapy of an androgen receptor positive sweat gland tumor, and anti‐estrogen therapy for an estrogen receptor positive sweat gland tumor were successful in single cases." (PMID 40277279, 2025).
T cell lymphoma (1 paper, 2013). "In addition, TCR gene rearrangement and clonal analysis, which is based on female X-chromosomal inactivation mosaicism and polymorphisms at PGK and androgen receptor (AR) loci, were found to play important roles in differentiating NK cell lymphoma from T cell lymphoma." (PMID 23958352, 2013).
teratocarcinoma (1 paper, 2013). A germ cell tumor characterized by the presence of an embryonal carcinoma component and a teratoma component. "Interestingly, HERV-K expression in teratocarcinoma cell lines can be further enhanced by androgens, although, it is still unknown whether the androgen receptor (AR) binds directly to HERV-K LTRs or acts via other host proteins." (PMID 24066280, 2013).
testicular disorder (1 paper, 2019). A non-neoplastic or neoplastic disorder affecting the testis. "Sex hormone receptors, such as AR, LHR, and FSHR, play significant roles in maintaining male sexual function, and their altered expression may be involved in aging-related testicular disorders." (PMID 31018574, 2019).
Thrombocytosis (1 paper, 2021). Increased numbers of platelets in the peripheral blood. "Sequencing analysis and human androgen receptor assays revealed that the majority of TN-ET patients exhibited polyclonal hematopoiesis, suggesting a possibility of reactive thrombocytosis in TN-ET." (PMID 34489506, 2021).
tongue cancer (1 paper, 2025). A malignant neoplasm affecting the tongue. "Red rectangles represent the hit genes involved in the treatment of tongue cancer (TERT, Bcl-2, CDK4/6, CDK2, VEGF, ER, RXR,c-KIT, MET, FGFR, PPAR8, PFFP, MMPs, CDK4, AR, F2, IGFR)." (PMID 39863836, 2025).
typhoid fever (1 paper, 2020). A bacterial infectious disorder contracted by consumption of food or drink contaminated with Salmonella typhi. "S. Typhi, a common foodborne pathogen that infects millions of people worldwide annually and results in typhoid fever, diarrhea, and death in severe cases, was the third most common species to be isolated and the fourth species to host the largest AR gene repertoire." (PMID 33234606, 2020).
urinary stones (1 paper, 2025). "Prostate infection, inflammation, or urinary stones involving the prostate can still lead to elevated serum PSA levels, whereas some patients with primary PCa exhibit negative AR and PSA results, obscuring clinicians’ judgment." (PMID 40746833, 2025).
uterine diseases (1 paper, 2022). "This article discusses the recent research progress of androgens in uterine diseases and explores the potential of AR as a therapeutic target for treating uterine diseases." (PMID 36358974, 2022). "Future studies should focus on developing new therapeutic strategies that precisely target specific AR and their related signaling pathways in uterine diseases." (PMID 36358974, 2022). "This review summarizes and discusses the progress of research on androgens and the involvement of AR in uterine diseases." (PMID 36358974, 2022).
uterine endometrioid carcinoma (1 paper, 2024). "In human clinical specimens, low expression of AR was associated with lower DFS in patients with uterine endometrioid carcinoma." (PMID 38890503, 2024).
varicocele (1 paper, 2020). A condition characterized by the dilated tortuous veins of the spermatic cord with a marked left-sided predominance. "From the network created, it is clear that the majority of the proteins involved in the acetylation process under the regulation of the androgen receptor are underexpressed in patients with bilateral varicocele." (PMID 32365753, 2020). "In varicocele patients, malfunctioning of the androgen receptor may be due to decreased testosterone levels." (PMID 32365753, 2020).
Varicose veins (1 paper, 2018). Enlarged and tortuous veins. "Our results coincide with these findings, showing downregulated AR gene expression in men with varicose veins." (PMID 30250632, 2018).
vulvar lichen sclerosus (1 paper, 2024). A chronic inflammatory disorder of unknown etiology that affects the vulva. "The expression of ER-α and ARs in vulvar lichen sclerosus have demonstrated a lack of AR expression in most instances." (PMID 38248777, 2024).
Williams syndrome (1 paper, 2016). "In addition, the AR seems to regulate genes related to oxytocin, estrogen and William’s syndrome." (PMID 27014003, 2016).
Wilson disease (1 paper, 2025). A very rare inherited multisystemic disease presenting non-specific neurological, hepatic, psychiatric or osseo-muscular manifestations due to excessive copper deposition in the body. "Because Wilson’s disease was a treatable autosomal recessive disorder, this trans-double mutation was consistent with the inheritance of AR genetic disorders." (PMID 40557282, 2025).
X-linked hypophosphatemia (1 paper, 2019). X-linked hypophosphatemia (XLH) is a hereditary renal phosphate-wasting disorder characterized by hypophosphatemia, rickets and/or osteomalacia, and diminished growth. "Interestingly, two skeletal disease mouse models also show similarity to the androgen receptor knockout; the Phex-deficient Hyp mouse model of X-linked hypophosphatemia and the AHSG knockout model of model of slipped capital femoral epiphysis (SCFE)." (PMID 30481257, 2019).
tumor (3,355 papers, 1996 to 2026). "In certain experimental settings, elevated androgen levels have been associated with reduced tumor growth, whereas AR activation has also been linked to signaling pathways involved in cell survival, migration, and invasiveness." (PMID 42121935, 2026). "We also identified an association between AR activity and tumor immunotherapy response using six independent, publicly available clinical datasets." (PMID 41486951, 2026). "In multivariable analysis, baseline tumor T stage, progesterone receptor expression, and AR expression were independently associated with DFS." (PMID 42200015, 2026). "The subsequent lymph-node biopsy confirmed progression, with most tumor cells showing complete loss of AR and PSA and strong expression of neuroendocrine markers, whereas a minor component retained adenocarcinoma-like morphology and faint PSA positivity." (PMID 41589227, 2026). "MET overexpression is associated with adverse pathological features, increased tumor aggressiveness, bone metastasis, lineage plasticity, and resistance to AR-targeted treatments." (PMID 42122259, 2026). "Tumor progression in PCa is strongly driven by androgen receptor (AR) signaling, which is closely linked to cellular metabolic reprogramming, highlighting metabolism as a potential therapeutic target." (PMID 42194907, 2026). "Emphasizing differing demethylase functions, KDM5D, which is located on the Y chromosome, acts as a tumor suppressor, and its loss leads to dysregulated AR signaling and resistance to ADT/taxane combinations in a large trial." (PMID 41601922, 2026). "We further evaluated the association between AR activity and immune cell abundances across all tumor types in TCGA, stratified by sex." (PMID 41486951, 2026). "In this study, we aimed to evaluate the anti-tumor activity of ATR-I in both AR+ and AR− CRPC cells and illustrate the underlying mechanism." (PMID 40087774, 2025). "Research indicates that progression is closely associated with androgen receptor (AR) signaling, loss of tumor suppressor genes, growth factor signaling, metabolic changes, the immune system, and the tumor microenvironment (TME)." (PMID 40427733, 2025). "This low expression of AR in tumor tissues is closely associated with advanced clinical stages and unfavorable prognoses in HNSCC patients." (PMID 40729027, 2025). "Again, the role of AR in ccRCC development and progression is inconclusive: even though AR was associated with tumor vasculogenesis and invasion, higher tumor AR levels were associated with better patient survival." (PMID 41228208, 2025). "Several follow-up studies linked the effect that MacroD1 had on tumor growth and progression with estrogen- and androgen-receptor signaling." (PMID 40817374, 2025). "AR-V7, a splice variant of the androgen receptor detected in circulating tumor cells (CTCs), predicts resistance to androgen receptor signaling inhibitors such as enzalutamide and abiraterone." (PMID 40868988, 2025). "This variability highlights the importance of precision medicine approaches that consider not only AR expression but also additional biomarkers, such as tumor mutational burden, immune checkpoint expression, and other factors that influence tumor behavior." (PMID 40940929, 2025). "Research has shown that CRPC is associated with the reactivation of AR activity in tumor cells and the restoration of tumor androgen levels through AIS." (PMID 39785769, 2025). "These distinct forms of AR are associated with different biological outcomes; monomers are suggested to favor oncogenic and proliferative signaling, while dimers tend to drive tumor-suppressive transcriptional programs." (PMID 41264145, 2025).